PLA2R1 (phospholipase A2 receptor 1)
Diseases named in the same sentence as PLA2R1 in open-access papers (continued):
Sharing a sentence is not in itself a finding about the gene and the disease.
idiopathic membranous nephropathy (74 papers, 2010 to 2026). "The SNPs in PLA2R1 is associated with idiopathic membranous nephropathy which is an autoimmune kidney disorder." (PMID 32678193, 2020). "PLA2R1 encodes the podocyte phospholipase A2 receptor (PLA2R) against which autoantibodies are found to be directed in membranous GN." (PMID 27933432, 2017). "We showed that in a large biopsy-proven European cohort, a missense variant (rs35771982) in PLA2R1 strongly associated (P = 1.4 × 10−14) with PLA2R antibody-positive membranous GN." (PMID 27933432, 2017). "The phospholipase A2 receptor (PLA2R1) is the major autoantigen in idiopathic membranous nephropathy (MN)." (PMID 32083137, 2019). "The associations of single nucleotide polymorphisms (SNPs) in PLA2R1 and HLA-DQA1, as well as HLA-DRB1*15:01-DQB1*06:02 haplotype with idiopathic membranous nephropathy (IMN) is well known." (PMID 30349113, 2018). "(ii) Assessment of glomeral expression of PLA2R1 and of THSD7A antigen in case of PLA2R1 seronegative MN deposits is at present mandatory in idiopathic membranous nephropathy." (PMID 29511687, 2018). "For idiopathic membranous nephropathy, SNPs in PLA2R1 (rs4664308) and HLA-DQA1 (rs2187668) have been shown to be important in Caucasians, while multiple loci are risk factors for IgA nephropathy in Asians." (PMID 27871254, 2016). "Although recent studies showed anti-PLA2R antibody plays a crucial role in idiopathic membranous nephropathy (IMN), detailed HLA mapping and interaction between the HLA genes and PLA2R1 have not been investigated in IMN." (PMID 27934873, 2016). "In idiopathic membranous nephropathy (IMN) the immune complexes are formed by circulating antibodies binding mainly to one of two naturally-expressed podocyte antigens: the M-type receptor for secretory phospholipase A2 (PLA2R1) and the Thrombospondin type-1 domain-containing 7A (THSD7A)." (PMID 31447839, 2019). "According to recent studies, the phospholipase A2 receptor 1 (PLA2R1) may be used as a biomarker to diagnose idiopathic membranous nephropathy (iMN)." (PMID 29843797, 2018). "Currently, several specific antigens, M-type receptor for secretory phospholipase A2(PLA2R1), thrombospondin type-1 domain-containing 7A(THSD7A), and neural epidermal growth factor-like 1 protein (NELL-1), are discovered associated with the onset of idiopathic membranous nephropathy (IMN)." (PMID 34703677, 2021). "(i) The prevalence of anti-PLA2R1 and anti-THSD7A antibodies is approximately 70% and 2% in adults with idiopathic membranous nephropathy." (PMID 29511687, 2018).
autoimmune disease (37 papers, 2016 to 2025). A disorder resulting from loss of function or tissue destruction of an organ or multiple organs, arising from humoral or cellular immune responses of the individual to their own tissue constituents. "Primary membranous nephropathy is a widely recognized autoimmune disease associated with podocyte antigens; the most important autoantigen is PLA2R1." (PMID 40845005, 2025). "This publication was a cornerstone in the history of MN as it provided evidence that iMN in adults is actually an autoimmune disease associated with the production of anti-PLA2R1 antibodies and introduced a new terminology of PLA2R1 related MN." (PMID 29511687, 2018). "Primary membranous nephropathy (MN) is an autoimmune disease caused by circulating antibodies against at least two known membrane proteins, Phospholipase A2 Receptor 1 (PLA2R1) and Thrombospondin Type-l Domain-Containing 7A (THSD7A), which are expressed on human podocytes." (PMID 30619370, 2018). "Anti-PLA2R1 or anti-THSD7A autoantibodies have been proposed as biomarkers of autoimmune disease activity and their blood levels should be regularly monitored in pMN to evaluate disease activity and predict outcomes." (PMID 29511687, 2018). "Primary MN is related to the autoimmune disorders caused by the presence of circulating antibodies against native podocyte antigens NEP, PLA2R1, and THSD7A or by antibodies developed against external antigens such as cationic bovine serum albumin (BSA) or aryl sulfatase." (PMID 29511687, 2018).
Autoimmunity (15 papers, 2016 to 2026). The occurrence of an immune reaction against the organism's own cells or tissues. "The podocyte-focused expression of PLA2R1, NTNG1, HTRA1, and NDNF is intriguing, highlighting antigen-initiated autoimmunity as causing podocyte injury and the subsequent MN pathogenesis." (PMID 40149392, 2025). "Kidney biopsies contained ineffaceable fingerprints of anti-PLA2R1 autoimmunity also in several glomeruli provided from second biopsy (after 7 years of well-conducted immunosuppression) and confirmed primary MN." (PMID 27493452, 2016). "Their role in the lipid signaling network in the skin may be mediated by binding to the phospholipase A2 receptor (PLA2R1) to influence pro-inflammatory signaling, autoimmunity, apoptosis, and aging." (PMID 32602849, 2020). "We suggest that circulating CD3−CD19+CD20−IgD−CD27highCD38high plasmablasts could be a new cellular biomarker of residual autoimmunity in PLA2R1 related MN." (PMID 27493452, 2016).
chronic kidney disease (14 papers, 2013 to 2026). Impairment of the renal function secondary to chronic kidney damage persisting for three or more months. "Our results indicate that suPAR’s strong associations with chronic kidney disease may be related to a suPAR-associated missense variant in the gene PLA2R1, and that variants in many genes related to glycosylation and glycoprotein biosynthesis pathways affect suPAR levels." (PMID 34079037, 2021). "Additionally, PLA2R1 is a top-upregulated gene in the podocytes of chronic kidney disease, acute kidney injury, and diabetic nephropathy, indicating its general role in causing podocyte injury." (PMID 40149392, 2025).
Hypertension (14 papers, 2018 to 2025). The presence of chronic increased pressure in the systemic arterial system. "Among them, SNPs in genes Ephx1, Pla2r1, and Ccdc28b were identified as candidates responsible for the concomitant manifestation of hypertension and signs of accelerated aging in OXYS rats." (PMID 32429546, 2020). "So far, genes Pla2r1 and Ccdc28b are not yet associated with hypertension; however, according to our results, they hold promise for further research into their role in the hypertensive state in OXYS rats and in many other rat strains modeling hypertension." (PMID 32429546, 2020).
diabetes (13 papers, 2023 to 2025). "Subgroup analysis comparing the cohorts homozygous for both the high-risk alleles for HLA-DQA1 and PLA2R1 (TT and AA respectively) with those not homozygous for both show a similar proportion of diabetes, both self-reported and through HES linkage." (PMID 37104302, 2023).
hepatitis B (13 papers, 2013 to 2026). "They found the low expression of anti-PLA2R antibodies in controls and in patients with hepatitis B-induced sMN; and circulating anti-PLA2R antibodies displayed a high correlation with PLA2R1 expression." (PMID 40943538, 2025).
lupus (13 papers, 2015 to 2026). "Genes that were significant with at least two variables include: BTNL2 for alopecia areata, NOD2 for Crohn’s disease, PLA2R1 for membranous neuropathy, LMO1 for neuroblastoma, and TNPO3, UBE2L3, HLA-DRA, and HIC2 for systemic lupus erythematosus." (PMID 26170196, 2015).
lupus nephritis (13 papers, 2017 to 2026). Glomerulonephritis in the context of systemic lupus erythematosus. "In individuals with anti-PLA2R1-associated MN or membrane lupus nephritis, or in a healthy control group, glomerular contactin 1 was lacking." (PMID 40502862, 2025). "However, even if their prevalence is much lower, the presence of anti-PLA2R1 antibodies in secondary MN (active sarcoidosis, lupus nephritis, and HBV infection) has been reported." (PMID 29511687, 2018). "However, as the pathogenic antigens (“keys”) of sMN differ (especially in patients with sMN who had lupus nephritis), besides the illegitimate PLA2R1 expression or other antigens of pMN, there may also be differences in the HLA susceptibility factors." (PMID 40943538, 2025). "Glomerular IgG4 staining has been most frequently associated with PLA2R1 deposition in pMN and is rarely observed in HBV-related MN and in general absent in the membranous form of lupus nephritis." (PMID 29511687, 2018). "However, the occurrence of anti-PLA2R1 autoantibodies in membranous lupus nephritis is very rare and they have never been observed in non-MN lupus nephritis." (PMID 29511687, 2018).
IgA nephropathy (12 papers, 2016 to 2024). "In contrast, none of the analysed control sera (PLA2R1-associated MN, minimal change disease, IgA nephropathy, healthy control) generated a similar Western blot signal." (PMID 34376704, 2021). "In contrast, sera from a control cohort (8 PLA2R1-antibody positive MN patients; 3 patients with minimal change disease and 3 patients with IgA nephropathy) did not give any positive signal." (PMID 34376704, 2021).
renal failure (12 papers, 2017 to 2025). "It will be interesting to investigate the association of PLA2R1 and HLA genotypes with the types and titers of antibodies against different epitopes as well as with disease severity, treatment response and progression to renal failure." (PMID 30349113, 2018).
sarcoidosis (12 papers, 2013 to 2025). Sarcoidosis is a multisystemic disorder of unknown cause characterized by the formation of immune granulomas in involved organs. "The reported relationship between sarcoidosis and MN seems to support this argument; a high prevalence of PLA2R1-associated MN among patients with MN associated with active sarcoidosis has been described." (PMID 33042109, 2020). "The expression of PLA2R1 antigen has been found in glomerular deposits in MN patients with sarcoidosis." (PMID 29511687, 2018). "An alternative hypothesis is that active sarcoidosis or chronic HBV infection prompts an immune response allowing the development of anti-PLA2R1 antibodies." (PMID 29511687, 2018).
glomerulonephritis (10 papers, 2017 to 2026). A renal disorder characterized by damage in the glomeruli. "Several podocyte antigens, such as PLA2R1, THSD7A, NELL1, HTRA1, and nephrin, are the primary targets of deleterious autoantibodies in glomerulonephritis patients." (PMID 40072092, 2025).
breast cancer (9 papers, 2015 to 2024). A primary or metastatic malignant neoplasm involving the breast. "In conclusion, our study suggests that PLA2R1 promoter methylation is a potentially useful diagnostic and prognostic biomarker in breast cancer." (PMID 32751713, 2020). "Our results indicated that PLA2R1 promoter hypermethylation was not only inversely correlated with PLA2R1 downregulation but also associated with the most aggressive subtypes of breast cancers." (PMID 32751713, 2020). "Next, we assessed if the PLA2R1 promoter average methylation level was associated with decreased PLA2R1 mRNA expression in human breast cancer tissues." (PMID 32751713, 2020). "Previous in vitro studies demonstrated that DNA hypermethylation was highly associated with the epigenetic silencing of PLA2R1 in breast cancer cell lines." (PMID 32751713, 2020). "The significant association of PLA2R1 promoter hypermethylation with TNBC implies its usefulness as a potential prognostic marker in breast cancer." (PMID 32751713, 2020). "Elevated levels of PLA2R1 are associated with pancreatic, gastric, prostate and ovarian carcinomas, while it is downregulated in leukemia, kidney, thyroid and breast carcinomas." (PMID 32751713, 2020). "Moreover, PLA2R1 promoter hypermethylation was found to be associated with aggressive subtypes of breast cancer, and PLA2R1 promoter hypermethylation was found to be a useful diagnostic and prognostic biomarker for breast cancer." (PMID 37345058, 2023). "Our results indicated that both PLA2R1 expression and its promoter methylation could be considered as potential diagnostic biomarkers in breast cancer as both can separate out benign from malignant breast tissues." (PMID 32751713, 2020). "Hence, we can conclude that PLA2R1 promoter hypermethylation is a potential diagnostic and prognostic biomarker in breast cancer." (PMID 32751713, 2020). "PLA2R1 promoter hypermethylation was associated with aggressive subtypes of breast cancer." (PMID 32751713, 2020). "In conclusion, PLA2R1 promoter hypermethylation is a potentially useful diagnostic and prognostic biomarker and could serve as a possible therapeutic target in breast cancer." (PMID 32751713, 2020). "We further explored whether PLA2R1 mRNA downregulation was associated with different molecular subtypes of breast cancer." (PMID 32751713, 2020). "Assessing promoter methylation as an epigenetic regulator that is associated with the differential expression of PLA2R1 in breast cancer may potentially define novel therapeutic targets, diagnostic and/or prognostic biomarkers." (PMID 32751713, 2020). "CENP-A acts as a transcriptional regulator and promotes DNMT1 (DNA Methyltransferase 1)-mediated PLA2R1 (Phospholipase A2 Receptor) promoter methylation, thereby reducing the expression level of PLA2R1 and augmenting breast cancer progression." (PMID 39273649, 2024). "In vitro studies have shown that PLA2R1 mRNA expression was reduced in several types of cancer, such as leukemia and kidney, thyroid and breast cancers." (PMID 37345058, 2023). "Together with previously published data, the results presented herein clearly underscore the role of DNA methylation in PLA2R1 gene regulation in mammary tumors." (PMID 32751713, 2020). "Our objective was to study the level of PLA2R1 mRNA expression and the methylation of its promoter in different histological grades and molecular subtypes of breast cancer." (PMID 32751713, 2020). "To explore the potential role of PLA2R1 in breast cancer tumorigenesis, we evaluated the expression of PLA2R1 mRNA." (PMID 32751713, 2020). "The fact that PLA2R1 mRNA was observed at low levels in breast cancer strongly supports its potential tumor suppressor role." (PMID 32751713, 2020). "We used qRT-PCR to evaluate the PLA2R1 mRNA expression and its promoter’s methylation in breast cancer tissue in comparison to breast fibroadenomas." (PMID 32751713, 2020).
breast cancer (continued). "This sheds light on the role of promoter methylation as an epigenetic regulator of PLA2R1 expression in breast cancer." (PMID 32751713, 2020). "Our results demonstrated a significant hypermethylation of the PLA2R1 promoter in breast cancer tissues compared to the benign controls." (PMID 32751713, 2020). "A statistically significant lower level of PLA2R1 mRNA expression (fold change = 0.052, p = 0.0005) was detected in breast cancer tissues compared to benign control." (PMID 32751713, 2020). "Hypermethylation of the PLA2R1 promoter in breast cancer is triggered by cellular myelocytomatosis (c-MYC)-mediated promoter methylation." (PMID 32751713, 2020). "In the present study, we explored the expression of PLA2R1 in breast cancer tissues of different histological grades and molecular subtypes in comparison to benign mammary tumors." (PMID 32751713, 2020). "Our study, to our knowledge, is the first to assess the expression of PLA2R1 and its promoter methylation as one of its epigenetic regulators in human breast cancer tissues." (PMID 32751713, 2020). "The web application bc-GenExMiner database version v4.4 was used to study the differential expression of PLA2R1 mRNA between various histological grades of DNA microarray and RNAseq datasets comprising 10,001 and 4712 breast cancer patients." (PMID 32751713, 2020). "Previous in vitro studies reported low expression of PLA2R1 mRNA in different types of cancer, such as leukemia, renal, thyroid and breast cancers." (PMID 32751713, 2020). "This is in line with previous findings by others who reported that PLA2R1 was shown to regulate several anti-tumor and anti-inflammatory responses, including proliferation, cell transformation, apoptosis and senescence in breast cancer." (PMID 32751713, 2020). "We performed bioinformatics analyses on available human breast cancer expression datasets to assess the PLA2R1 mRNA expression." (PMID 32751713, 2020). "Our data indicated that the differential expression of PLA2R1 reflected the degree of differentiation of breast cancer cells, which supports its clinical usefulness." (PMID 32751713, 2020). "Our results describe, for the first time, the expression of PLA2R1 and the methylation of its promoter in human breast cancer tissues." (PMID 32751713, 2020). "A significant downregulation of PLA2R1, together with hypermethylation of the promoter was detected in breast cancers of different histological grades and molecular subtypes when compared to benign breast tissues." (PMID 32751713, 2020). "Large-scale clinical studies are required to assess the prognostic relevance of PLA2R1 and its promoter methylation to breast cancer outcomes and treatment responses." (PMID 32751713, 2020). "To validate the results obtained from our bioinformatics analysis, we assessed the mRNA expression of PLA2R1 in different histological grades of human breast cancer." (PMID 32751713, 2020). "In the present study, we showed that significant downregulation of PLA2R1 was detected in breast cancers of different histological grades and molecular subtypes when compared to benign breast tissues." (PMID 32751713, 2020). "Phospholipase A2 receptor 1 (PLA2R1) expression and its role in the initiation and progression of breast cancer are an unresolved issue." (PMID 32751713, 2020). "PLA2R1 expression and its role in the tumorigenesis of breast cancer are still not completely understood." (PMID 32751713, 2020). "Although the HER2-positive, luminal A and luminal B subtypes of breast cancer demonstrated lower expression of PLA2R1 mRNA with median fold changes (0.029, 0.232 and 0.158, respectively), none of these differences approached statistical significance." (PMID 32751713, 2020). "PLA2R1 promoter hypermethylation was detected in leukemic cells, renal cell carcinoma and breast cancer cell lines." (PMID 32751713, 2020).